BRCA1 (BRCA1 DNA repair associated)
Diseases named in the same sentence as BRCA1 in open-access papers (continued):
Sharing a sentence is not in itself a finding about the gene and the disease.
tumor (continued). "By contrast, PR-low/TP53m tumours rarely demonstrate such mutations; however, around one third (31.6%, 6 of 19) display mutation of BRCA1/2, suggesting exploration of poly-(ADP-ribose) polymerase (PARP) inhibitor efficacy in this population is warranted." (PMID 34079052, 2021). "Many BRCA1 mutations in tumours arise in exon 11, the largest exon of the gene encoding for ∼60% of the protein." (PMID 33755171, 2021). "The artificial FFPE tumor sample provided contained a cell line engineered to generate the BRCA1 c.68_69del variant." (PMID 34643925, 2021). "The distinct tumor-immune microenvironments in BRCA1 and BRCA2-deficient tumors are modulated by distinct mutational and copy-number profiles, which can predispose to distinct immune checkpoint blockade response." (PMID 33540843, 2021). "Collectively, these findings suggest that excess adiposity drives inflammation and local estrogen production, which ultimately promotes tumor growth in hyperadipose individuals with DNA repair insufficiency owing to germline BRCA1 or BRCA2 mutations." (PMID 33649363, 2021). "Whereas, it is also possible that irradiated BRCA1-mutnat tumor cells are liable to having mutations for insufficiency of DNA damage repair." (PMID 33767581, 2021). "We have previously shown that PARP inhibitors can significantly delay tumor development in BRCA1-deficient mice." (PMID 33441637, 2021). "Our observation is also supported by the report of tumor loss of heterozygosity in serous/serous-like EC with germline BRCA1 mutations (two of three cases)." (PMID 33917078, 2021). "Of the 179 known BC susceptibility SNPs identified through GWAS in the general population, only 10 showed evidence of interaction with BRCA1 or BRCA2 mutation carrier status after taking the tumour ER-status into account." (PMID 33597508, 2021). "In the first case of a deletion of exon 20 in BRCA1, re-evaluation of the bioinformatic variant calls revealed the deletion also in the tumor DNA and led to a correction of the initial diagnostic report." (PMID 34202525, 2021). "This activation led to enlarged tumor blood vessels and accelerated tumor growth, as observed in a BRCA1-deficient mouse model." (PMID 33672287, 2021). "Typically, pathogenic BRCA1/2mut are detected through germline testing of normal whole blood or saliva DNA, or somatic testing of tumour tissue." (PMID 33671468, 2021). "Recent evidence in mouse models of breast and colorectal cancer, suggest that BRCA2-deficient tumours are more susceptible to ICIs than BRCA1-deficient tumour." (PMID 35096825, 2021). "The combination therapy triggers more significant antitumor effects against tumor growth than those achieved with monotherapy in xenograft mice bearing BRCA1/2-wildtype or mutated TNBC tumors." (PMID 34948368, 2021). "BRCA1 encodes a 190 kD nuclear phosphorylation protein, which maintains genomic stability and functions as a tumor suppressor." (PMID 34830941, 2021). "Consistently, pharmaceutical inhibition of Pdgfrβ or Pkcα activity suppressed Brca1-deficient tumor initiation and progression." (PMID 33478572, 2021). "Despite representing distinct tumour types, there has been limited success in identifying gene expression profiles related to BRCA1 and BRCA2 pathogenic variants in either tumour or normal tissue." (PMID 34287743, 2021). "In fact, 53BP1 depletion is known to restore BRCA1-independent HR in BRCA1-deficient tumor cells and to confer resistance to PARPi." (PMID 34439286, 2021). "This study shows an interesting concept that some tumor types with BRCA1 alternative splice variants have intrinsic ability to promote their own invasiveness." (PMID 35008272, 2021). "Tumor-selective loss of the remaining BRCA1/2 allele is a key event determining antitumor activity of platinum compounds and PARP inhibitors." (PMID 34454564, 2021).
tumor (continued). "Homozygous C61G mice are embryonic lethal and develop spontaneous tumors similar to BRCA1 null mice, whereas mouse tumor cells carrying the C61G variant show a poor response to olaparib and cisplatin and rapidly develop resistance." (PMID 36860287, 2021). "A tumor is considered HRD if there is a BRCA1/2 mutation, or a genomic instability score (GIS) of ≥42." (PMID 34711195, 2021). "When PARP inhibitors are used upon an existing BRCA1/2 mutation, DNA repair in tumor cells is further limited, thereby resulting in lethality, i.e., the “synthetic lethality” phenomenon, which is the treatment principle of PARP inhibitors." (PMID 35047380, 2021). "Together, these data suggest that reconstitution of Gata3 activates MET and suppresses Brca1-deficient tumor development and metastasis." (PMID 34373738, 2021). "PARP inhibitors, such as olaparib, inhibit homologous recombination during the repair process after DNA damage and thus, exert their antitumor effects by inducing the apoptosis of tumor cells harboring germline BRCA1/2 mutations." (PMID 34209310, 2021). "Firstly, tumor cells can perform mutational reversion of BRCA1/2, which causes restoration of the HR DNA repair pathway." (PMID 34884434, 2021). "HR deficiency was defined as either a deleterious tumour BRCA1/2 (tBRCA) mutation or a predefined HRD score ≥ 42, which was determined in 57.8% (48/83) of TNBC patients." (PMID 34465315, 2021). "Tumours of these patients almost universally lose both functional copies of the BRCA1 or BRCA2 gene, either by loss of heterozygosity (LOH) of the wild-type allele or, more rarely, by the acquisition of a somatic mutation in the wild-type locus." (PMID 35008208, 2021). "These somatic mutations (in the presence of a germline BRCA mutation) restore BRCA1/2 function and are associated with a decrease in the response to current treatment and tumor progression." (PMID 33918338, 2021). "Significantly higher PAF-AH levels were detected in tumor biopsies and in the serum of BRCA1 mutation carriers compared to BRCA WT patients." (PMID 34206491, 2021). "Several poly (adenosine diphosphate-ribose) polymerase (PARP) inhibitors are now in clinical use for tumours with defects in BReast CAncer genes BRCA1 or BRCA2 that result in deficient homologous recombination repair (HRR)." (PMID 34445211, 2021). "Many other mouse models of germline partial loss of function of Brca1 and other HR genes have been generated, and these studies established the importance of HR for tumor suppression in vivo." (PMID 33923105, 2021). "For example, early studies were confounded by differences in oestrogen receptor (ER) status of BRCA1-associated tumours compared to sporadic." (PMID 34287743, 2021). "This patient was sequenced at FoundationOne using tumor only and called a BRCA1 (V1804D) mutation, among others." (PMID 34504655, 2021). "One tumour showed an alteration in FANCA, one tumour showed an alteration in FANCM (with a concomitant BRCA1 P/LP variant), and one tumour showed an alteration in RAD51C." (PMID 34680387, 2021). "Apart from Mrc2, we identified some other DEGs between the BRCA1 deficient luminal cells and tumor cells." (PMID 34815798, 2021). "InCeT-TLZ did not alter the biological effects of TLZ as it induced DNA damage and cell death in BRCA1-deficient tumor cells." (PMID 33441637, 2021). "The objective of this review is to provide significant insights into the mechanisms by which BRCA1 mutations contribute to the metastatic and aggressive nature of the tumor cells." (PMID 35008272, 2021).
tumor (continued). "Recent studies have found that the cGAS-STING pathway being activated in the setting of genome instability can be attributed to dMMR 38, PARP inhibitor treatment, or functional loss of BRCA1/2 genes 39, and it predicts a better prognosis of tumor patients." (PMID 34158843, 2021). "We also analyzed the tumor phenotype present in mutations other than BRCA1/2 in order to obtain prognostic and clinical–pathological information." (PMID 34204722, 2021). "TBCRC 048 evaluated the role of olaparib in homologous recombination deficient tumours due to genomic alterations other than germline BRCA1/2 mutations; clinically relevant activity was reported in patients with germline PALB2 and somatic BRCA1/2 mutations." (PMID 33520003, 2021). "Confirming this role, targeted deletion of Pdgfrβ in Brca1-deficient tumor cells promoted cell death, induced mesenchymal-to-epithelial transition, and suppressed tumorigenesis." (PMID 33478572, 2021). "Molecular testing of tumor tissue identified an additional five and three patients with somatic BRCA1 and BRCA2 mutations, respectively." (PMID 33668244, 2021). "It is to be noted that no one tumor had a deep (homozygous) co-deletion of both BECN1 and BRCA1, and only one tumor had a deep deletion of BRCA1 associated with shallow deletion of BECN1." (PMID 33670664, 2021). "To determine the mechanisms associated with inhibition of tumor progression by Pdgfrβ and Pkcα inhibitors, we analyzed Brca1-deficient tumors by western blot." (PMID 33478572, 2021). "Although the greatest efficacy of PARPi has been observed in tumors with BRCA1/2 mutations, consensus is that synthetic lethality insufficiently explains PARPi-related anti-tumor activity." (PMID 34631532, 2021). "Studies of BRCA1/2-mutated tumours in breast and ovarian cancer have shown higher frequency of TILs compared to HR-proficient tumours." (PMID 34572747, 2021). "Again, these results confirm that the inhibition of Pdgfrβ and Pkcα activity promotes MET and reduces Brca1-deficient tumor initiating potential." (PMID 33478572, 2021). "The BRCA1 is a tumour-suppressing gene encoding a large protein that is involved in numerous essential biological processes, including DNA damage repair, cell cycle control and transcriptional regulation." (PMID 34199079, 2021). "Cells deficient in RAD51-mediated HDR through the inactivation of tumor suppressor genes like BRCA1 or BRCA2 exhibit hypersensitivity to poly-ADP ribose polymerase 1 (PARP1) inhibitors." (PMID 33662256, 2021). "Tumor cells with mutation in BRCA1 or BRCA2 genes exhibit defective HR (referred to as BRCAness phenotype) and are pronounceably hypersensitive to ATM and PARP inhibition." (PMID 34718714, 2021). "PAF-AH expression was also investigated by IHC in tumor tissue of BRCA1 mutation carriers (n = 107)." (PMID 34206491, 2021). "Olaparib as a single agent was effective in PDX models with BRCA1 mutation, but several individual tumors were shown to escape therapy, and overall tumor burden was increased by the experimental endpoints." (PMID 34465787, 2021). "These recommendations focus on the identification of pathogenic tumor and/or germline variants (mutations) in BRCA1/2 and other genes participating in the homologous recombination repair (HRR) of double-strand DNA breaks." (PMID 34141624, 2021). "The first most clinically relevant application of synthetic lethality is the use of PARP inhibitors in BRCA1‐ or BRCA2‐deficient tumours." (PMID 34254730, 2021). "We used next generation sequencing using a targeted panel to prospectively analyse 274 tumours and identified 50 with a BRCA1/2 pathogenic variant." (PMID 34680387, 2021). "Reconstitution of Gata3 in Brca1-deficient tumor cells activated mesenchymal-epithelial transition, suppressing tumor initiation and metastasis." (PMID 34373738, 2021).
tumor (continued). "Due to the limited number of patients, no subgroup analyses regarding a comparison with 18F-FDG as well as correlation with histologic classification and BRCA1/2 mutation status for the same tumor type were possible." (PMID 34050777, 2021). "These patients had a BRCA1 frameshift somatic variant detected in tumor samples with a VAF of 5.4% and 53%, respectively." (PMID 34660321, 2021). "We now know BRCA1 is a tumour suppressor gene, given that tumour formation in carriers of heterozygous loss-of-function mutations is frequently driven by loss of the wild type allele." (PMID 33755171, 2021). "Treatment of Brca1-mutated tumor-bearing mice with AZD2281 was found to inhibit tumor growth alone and to potentiate the clinical effectiveness of DNA-damaging anticancer agents when used in a combined treatment regimen 10,11." (PMID 33767581, 2021). "In BRCA1/2 mutated tumor cells, DNA double-stranded repair function is lost; since PARP inhibitors can block single-stranded DNA repair, this results in a “synthetic lethal” effect that leads to the death of tumor cells." (PMID 35071013, 2021). "The reliance of cell survival on alternative DNA repair mechanisms when key repair genes, such as BRCA1/2, are mutated, likely plays a significant role in persistence of many tumor types, including breast and ovarian." (PMID 34070674, 2021). "A high γδ T cell density was significantly associated with younger age, higher tumor histological grade, adjuvant chemotherapy, BRCA1 promoter methylation, TIL density, and PD-L1 and PD-1 expression." (PMID 33673133, 2021). "Targeted deletion of Pdgfrβ in Brca1-deficient tumor cells inactivated Pdgfrβ-Pkcα signaling, promoted cell death, induced MET, and suppressed tumorigenesis." (PMID 33478572, 2021). "The potential to exploit this scenario became apparent when two independent studies reported dramatic cytotoxicity of PARP inhibitors in the context of deficiencies in the tumor suppressor genes BRCA1 and BRCA2 (breast cancer susceptibility genes 1 and 2)." (PMID 33888558, 2021). "When BRCA1/2 mutations are found by NGS in tumor-tissue specimens, it is necessary to distinguish between somatic and germline mutations." (PMID 34209310, 2021). "When RAD52 is knocked out in BRCA1- or BRCA2-deficient tumor cells, HRR frequency is significantly reduced." (PMID 34484285, 2021). "Evaluation of the paired tumor germline cohort in this study provides important insights into BRCA1/2 variants in HGSC, which, in turn, has implications for service delivery planning and genetic testing models." (PMID 33030818, 2021). "Tumor development involves somatic inactivation of the remaining BRCA1/2 allele, therefore BRCA1/2-driven BCs are characterized by a selective deficiency in DNA repair by homologous recombination (HRD)." (PMID 34681592, 2021). "Of the 14 patients with BRCA1/BRCA2 somatic variants identified in tumor samples, two were from the naive treatment group (OC04 and OC28)." (PMID 34660321, 2021). "PALB2, the partner and localizer of BRCA2 and the bridge between BRCA1/2, located in 16p12.2, is a tumor-suppressor gene that encodes a protein essential for homologous recombination in collaboration with BRCA2 during DNA double-stranded break repair." (PMID 34298749, 2021). "A recent report has suggested that PARP inhibitor Olaparib treatment induces changes in the tumor microenvironment of BRCA1-mutated TNBC cells and induces CD8+ T cell infiltration and activation in vivo." (PMID 35008272, 2021). "While the therapeutic value of PARP inhibitors is often determined based on BRCA1/2 mutational status, other clinically important tumor suppressor genes also contribute to synthetic lethality." (PMID 34711195, 2021). "Given the potential synergy between PARP inhibitors and ICI, multiple studies have been developed to explore the clinical applications and efficacy of this combination therapy in tumours harbouring BRCA1/2 or other DDR gene mutations." (PMID 34572747, 2021).
tumor (continued). "The groups of patients with MET-positive vs. MET-negative tumors were comparable in age, BRCA1/2 mutation status, and amount of tumor remaining after debulking surgery." (PMID 34069138, 2021). "Consistent with our transcriptome analysis, in situ expression analysis of BRCA1-associated tumours showed significantly greater EN1 expression variability (p = 6.7 × 10−04)." (PMID 34287743, 2021). "Recently, high-throughput sequencing of breast and ovarian tumours revealed that common oncogene amplifications (i.e. CCND1 encoding cyclin D1 in breast cancer and CCNE1 encoding cyclin E in ovarian cancer) rarely occur in tumours with BRCA1/2 gene mutations." (PMID 34389725, 2021). "To genetically confirm the role of Brca1 in regulating the methylation of Gata3 gene we treated p18-/- (Brca1 proficient) and p18-/-;Brca1MGKO (Brca1 deficient) tumor cells with DAC." (PMID 34373738, 2021). "Overall, 28% of carriers of HR-related gene variants had a presence of HR-deficiency associated tumor mutational signature, which increased to 86% of carriers when only well-recognized HR genes (BRCA1, PALB2 and RAD51C) were included." (PMID 33917078, 2021). "In this review, we discuss the mechanisms by which BRCA1 mutations contribute to the metastatic and aggressive nature of the tumor cells." (PMID 35008272, 2021). "PARP, BRCA1 and BRCA2 are components required for efficient DNA repair, and therefore, tumour cells that already harbour a BRCA1 or BRCA2 mutation will have increased sensitivity to PARP inhibitor therapy." (PMID 34254730, 2021). "In fact, of the two treatment-naive patients with somatic BRCA1 variants identified in tumor samples, in one of them we detected in ctDNA a BRCA1 somatic variant that was present in the tumor with a VAF of 53%, but not in the one that had a VAF of 5.4%." (PMID 34660321, 2021). "The most common HR-disrupting mutations in tumor cells involving BRCA1 and BRCA2 are single-nucleotide mutations, short insertions or deletions that lead to frame-shifts." (PMID 34884434, 2021). "This study makes the important observation that tumors from patients with BRCA2 mutations had increased PD‐L1 mRNA expression and a higher percentage of PD‐L1 protein expression in tumor‐associated ICs compared to patients with BRCA1 mutations." (PMID 33811746, 2021). "Treatment of Brca1-mutated tumor-bearing mice with olaparib was found to induce synthetic lethality by disrupting homologous recombination and inhibiting other repair pathways 10,11,12,13." (PMID 33767581, 2021). "In particular, high levels of PAF-AH were found in tumor tissue and in the serum of BRCA1 mutation carriers." (PMID 34206491, 2021). "The possibility of the detection of reversion mutations is one more argument for the superiority of BRCA1/2 sequencing in tumor tissue." (PMID 33918338, 2021). "Here, we establish a diagnostic pipeline using high-resolution microscopy and laser microcapture microscopy to test for BRCA1/2 mutations in the tumor at the single-cell level, followed by deep next-generation sequencing of various tissues from the patient." (PMID 34068254, 2021). "For example, significant expression deficiency or LOH of the BRCA1 or BRCA2 genes can often be masked by the presence of these genes in the normal cells in the tumor biopsy." (PMID 34145376, 2021). "Platinum salts should be more effective in TNBC due to more frequent damage of the repair system of DNA breaks caused by germline mutations in tumor suppressor genes (BRCA1/2, PALB) or by somatic mutation leading to homologous recombination deficiency." (PMID 33808149, 2021). "Previous studies have also demonstrated that ATR inhibitors exhibit strong antitumor activity against HRR-deficient tumor models, such as those that are deficient in BRCA1/2, RAD51, or ATM-mutated." (PMID 34552099, 2021).